WFIKKN2 (WAP, follistatin/kazal, immunoglobulin, kunitz and netrin domain containing 2)
Description:
Protease-inhibitor that contains multiple distinct protease inhibitor domains. Probably has serine protease- and metalloprotease-inhibitor activity. Inhibits the biological activity of mature myostatin, but not activin (By similarity).
Synonyms: GASP-1; hGASP-1; WFIKKNRP; WFDC20B
Tractability: Antibody: UniProt places it where antibodies can reach, with medium confidence; UniProt predicts a signal peptide or a membrane-spanning region; its Gene Ontology location is reachable by antibodies, with medium confidence.
Gene: Protein-coding gene on chromosome 17 (50,834,650 to 50,842,353, forward strand). Ensembl gene ENSG00000173714.
Subcellular location: Secreted
Gene Ontology:
Molecular function: protein binding; receptor antagonist activity; transforming growth factor beta binding; peptidase inhibitor activity; serine-type endopeptidase inhibitor activity
Biological process: negative regulation of transforming growth factor beta receptor signaling pathway; transforming growth factor beta receptor signaling pathway
Cellular component: extracellular region
Genetic constraint (gnomAD): Loss-of-function variants: 25 observed, 41.56 expected, observed/expected ratio (o/e) 0.6, 90% interval 0.44 to 0.84. The upper end of that interval is the gene's LOEUF score, 0.84, which puts it in group 3 of 6, group 1 being the genes least tolerant of losing a copy. Missense variants: 770 observed, 846.15 expected, observed/expected ratio (o/e) 0.91, 90% interval 0.86 to 0.97. Synonymous variants: 345 observed, 342.11 expected, observed/expected ratio (o/e) 1.01, 90% interval 0.92 to 1.1.
Homologues: Orthologues: chimpanzee WFIKKN2 (99% identical), macaque WFIKKN2 (99% identical), dog WFIKKN2 (94% identical), pig WFIKKN2 (93% identical), rat Wfikkn2 (93% identical), mouse Wfikkn2 (92% identical), rabbit WFIKKN2 (92% identical), guinea pig WFIKKN2 (90% identical), tropical clawed frog wfikkn2 (70% identical), Drosophila melanogaster CG7565 (10% identical), Caenorhabditis elegans Y55F3BR.2 (9% identical), Caenorhabditis elegans C02F12.5 (7% identical), and 1 more. Paralogues in human: WFIKKN1 (53% identical), AMBP (12% identical), SPINT1 (12% identical), TFPI (11% identical), KIAA0319L (11% identical), KIAA0319 (10% identical), TFPI2 (9% identical), WFDC8 (9% identical), EPPIN (8% identical), LRP11 (7% identical), SPINT2 (7% identical), SPINT4 (4% identical), and 1 more.
Diseases named in the same sentence as WFIKKN2 in open-access papers:
WFIKKN2 is named in the same sentence as 9 diseases in open-access papers, as found by Europe PMC text mining. Sharing a sentence is not in itself a finding about the gene and the disease. The quoted sentences say what the papers report.
metabolic syndrome (1 paper, 2024). A cluster of metabolic risk factors for CARDIOVASCULAR DISEASES and TYPE 2 DIABETES MELLITUS. "WFIKKN2 is the only protein that was reported in a previous plasma proteomic study that presented 53 proteins associated with metabolic syndrome defined by the simultaneous clustering of cardio-metabolic risk factors, although it was determined to have no causal effects on metabolic syndrome." (PMID 38649851, 2024).
Obesity (1 paper, 2024). Accumulation of substantial excess body fat. "A recent study identified six proteins (LEPR, IGFBP1, WFIKKN2, AGER, DPT, and CTSA), including WFIKKN2, which may have a causal role in the development of obesity." (PMID 39273278, 2024).
type 2 diabetes (1 paper, 2022). "Proteins that we identify through EpiScore associations, such as NTR domain-containing protein 2 (WFIKKN2), have also been causally implicated in type 2 diabetes onset through Mendelian randomisation analysis." (PMID 35023833, 2022).
cancer (2 papers, 2020 to 2025). A tumor composed of atypical neoplastic, often pleomorphic cells that invade other tissues. "Following identification of HER2-coamplified genes via copy number variation analysis, a series of bioinformatic tools were used that eventually led to the identification of WFIKKN2 as a novel cancer-associated blood plasma protein." (PMID 41194281, 2025). "TOB1 and its neighbouring gene WFIKKN2 are focally amplified in breast cancer and pan-cancer, suggesting a complex role in cancer." (PMID 32025015, 2020).
cardiovascular diseases (1 paper, 2024). "Nonetheless, it was claimed that there was a bidirectional causal relationship of WFIKKN2 with BMI, which is an important risk factor for cardiovascular diseases." (PMID 38649851, 2024).
tumor (1 paper, 2025). "SLPI, WFDC2, WFIKKN2, and WFDC1 consistently showed low expression across tumor types, whereas WFDC5, WFDC3, and WFIKKN1 displayed heterogeneous expression profiles." (PMID 40350979, 2025).
WFIKKN2 also shares sentences with these, for which no sentence is quoted: breast carcinoma (1 paper); dementia (1); diabetes (1).